HES7 (hes family bHLH transcription factor 7)
Description:
Transcriptional repressor. Represses transcription from both N box- and E box-containing promoters. May with HES1, cooperatively regulate somite formation in the presomitic mesoderm (PSM). May function as a segmentation clock, which is essential for coordinated somite segmentation (By similarity).
Synonyms: hHes7; bHLHb37; SCDO4
Tractability: No criterion of Open Targets' tractability assessment is met for any kind of drug.
Gene: Protein-coding gene on chromosome 17 (8,120,592 to 8,124,106, reverse strand). Ensembl gene ENSG00000179111.
Subcellular location: Nucleus
Subcellular location (Human Protein Atlas): Nucleoplasm; Nucleoli
Pathways (Reactome):
Developmental Biology: Somitogenesis
Gene Ontology:
Molecular function: protein binding; sequence-specific double-stranded DNA binding; DNA binding; DNA-binding transcription factor activity, RNA polymerase II-specific; RNA polymerase II cis-regulatory region sequence-specific DNA binding; protein dimerization activity; RNA polymerase II transcription regulatory region sequence-specific DNA binding
Biological process: anterior/posterior pattern specification; mesoderm development; negative regulation of transcription by RNA polymerase II; regulation of neurogenesis; negative regulation of DNA-templated transcription; regulation of DNA-templated transcription
Cellular component: chromatin; nucleus
Genetic constraint (gnomAD): Loss-of-function variants: 8 observed, 10.93 expected, observed/expected ratio (o/e) 0.73, 90% interval 0.43 to 1.32. The synonymous counts are far from expectation, so gnomAD's model fits this gene poorly and the ratio says little. Missense variants: 356 observed, 240.93 expected, observed/expected ratio (o/e) 1.48, 90% interval 1.35 to 1.61. Synonymous variants: 170 observed, 112.26 expected, observed/expected ratio (o/e) 1.51, 90% interval 1.34 to 1.72.
Homologues: Orthologues: chimpanzee HES7 (94% identical), pig HES7 (93% identical), dog HES7 (92% identical), guinea pig HES7 (92% identical), macaque HES7 (91% identical), mouse Hes7 (90% identical), rabbit HES7 (81% identical), rat Hes7 (78% identical), zebrafish her1 (35% identical), tropical clawed frog esr-5 (34% identical), zebrafish her11 (23% identical), Drosophila melanogaster cwo (21% identical), and 8 more. Paralogues in human: HES4 (24% identical), HEY2 (23% identical), HES1 (23% identical), HEY1 (23% identical), HES6 (22% identical), BHLHE41 (22% identical), HES2 (21% identical), HES5 (21% identical), HES3 (20% identical), BHLHE40 (19% identical), HEYL (19% identical), HELT (17% identical).
Diseases named in the same sentence as HES7 in open-access papers:
HES7 is named in the same sentence as 26 diseases in open-access papers, as found by Europe PMC text mining. Sharing a sentence is not in itself a finding about the gene and the disease. The quoted sentences say what the papers report.
spondylocostal dysostosis (9 papers, 2016 to 2025). Spondylocostal dysplasia is a rare genetic disorder characterized by defects of the bones of the spine (vertebrae) and abnormalities of the ribs. "Human pathogenic alterations in MESP2 and HES7 cause spondylocostal dysostosis characterized by rib and vertebral abnormalities." (PMID 40259859, 2025). "Mutations in HES7 cause spondylocostal dysostosis in humans and dogs, short-tailed trait in cats and affect skeleton formation as well as body length in mice." (PMID 28454565, 2017). "HES7 mutations cause spondylocostal dysostosis (SCD), a rare developmental congenital abnormality of the axial skeleton in humans." (PMID 27560986, 2016). "Spondylocostal dysostosis (SCD) is caused by the DLL3, MESP2, LFNG, and hairy-and-enhancer-of-split-7 (HES7) genes, which are also related to the Notch signaling pathway." (PMID 31275352, 2019). "Similarly, the other genes associated with recessive spondylocostal dysostosis (MESP2, LFNG, and HES7) have been associated with regulating Notch-signaling activity during somitogenesis." (PMID 36506336, 2022).
autosomal recessive spondylocostal dysostosis (2 papers, 2015 to 2016). "In humans, HES7 missense changes p.R25W, p.I58V and p.D186Y cause autosomal recessive spondylocostal dysostosis (SCDO4, OMIM:613686)." (PMID 27030474, 2016).
bladder cancer (1 paper, 2024). "However, the gene HES7 is part of the notch signaling pathway, which can influence bladder cancer progression." (PMID 38672670, 2024).
cannabis dependence (1 paper, 2022). Physical and psychological dependence on the drug cannabis. "HES7/PER1 on chromosome 17 may represent a meaningful risk factor in the development of cannabis dependence and its severity." (PMID 36135314, 2022).
classical Hodgkin lymphoma (1 paper, 2025). "A previous study had suggested that HES7 transcriptional inhibition of Gli1 expression and Hedgehog signaling may cause drug resistance to PD-1 therapy in classical Hodgkin lymphoma." (PMID 40404896, 2025).
Dextrocardia (1 paper, 2015). The heart is located in the right hand sided hemithorax. "A novel homozygous missense mutation c.1451A > C (p.H484P) in exon 9 of the CTC1 gene and a rare 3′UTR known dbSNP variation (c.*556 T > C) in HES7 were identified as the plausible candidates associated with this complex phenotype of Coats plus and dextrocardia." (PMID 25928698, 2015).
leukodystrophy (1 paper, 2021). Leukodystrophies are a group of rare, progressive, metabolic, genetic diseases that affect the brain, spinal cord and often the peripheral nerves. "As proof of concept, we present novel mouse models for multiple known human diseases representing different developmental etiologies, including segmentation defects (Hes7), leukodystrophy (Galc) and neuromuscular disease (Clcn1 and Large1)." (PMID 34142127, 2021).
lung adenocarcinoma (1 paper, 2019). A carcinoma that arises from the lung and is characterized by the presence of malignant glandular epithelial cells. "Three of the nine-examined early EMT hallmark genes, GALNT6, SPARC and HES7, were up-regulated specifically in the early stages of lung adenocarcinoma (LUAD) and confirmed by TCGA patient transcriptome data." (PMID 31296175, 2019). "By analyzing LUAD dataset from TCGA, we found three EMT markers (GALNT6, SPARC and HES7) among the nine in vitro identified genes with known function are also up-regulated in specifically in early stage lung adenocarcinoma patients." (PMID 31296175, 2019).
lung carcinoma (1 paper, 2019). "Strikingly, three early EMT hallmark genes GALNT6, SPARC and HES7 show the similar stage-specific expression pattern in LUAD TCGA samples, which can be further studied for diagnosis of early stages of lung cancer and for developing anticancer drugs." (PMID 31296175, 2019).
scoliosis (1 paper, 2015). A congenital or acquired spinal deformity characterized by lateral curvature of the spine. "In this study, a human patient with scoliosis was found to be heterozygous for a non-synonymous SNP in HES7 that impaired the autorepressive activity of the protein." (PMID 25659135, 2015).
situs inversus (1 paper, 2015). A congenital condition in which there is complete right-to-left reversal of the position of the major thoracic and abdominal organs (that is, they are arranged in a mirror image of the normal positioning). "For example, three of seven patients with the same HES7 mutation displayed dextrocardia with situs inversus, while this syndrome was absent among other SCD4 patients." (PMID 25659135, 2015).
cancer (1 paper, 2017). A tumor composed of atypical neoplastic, often pleomorphic cells that invade other tissues. "Finally, we observed that basal expression of CSC-related genes (ID1, CD44, HES7 and TCF3) significantly correlate with ONC201 efficacy in >1000 cancer cell lines and combining the expression of multiple genes leads to a stronger overall prediction." (PMID 28767654, 2017).
HES7 also shares sentences with these, for which no sentence is quoted: Blindness (1 paper); cleft palate (1); Coats plus syndrome (1); COVID-19 (1); genetic disorder (1); infantile hemangiomas (1); melanoma (1); neuroblastoma (1); neuromuscular disease (1); osteogenesis imperfecta (1); Spina bifida occulta (1); Spondylocostal dysostosis 4 (1); spondylothoracic dysostosis (1); tumor (1).